CLDN2 (claudin 2)
Diseases named in the same sentence as CLDN2 in open-access papers (continued):
Sharing a sentence is not in itself a finding about the gene and the disease.
tumor (59 papers, 2009 to 2026). "The findings support a model in which CLDN-2 expression aligns with an invasion-associated epithelial configuration linked to tumor budding and nodal dissemination." (PMID 42279354, 2026). "Replacement pattern was associated with Claudin 2, therefore, with tumour dissemination, and early cancer cell survival." (PMID 41245580, 2025). "High CLDN2 mRNA levels from tumor samples were associated with worse overall survival in three independent datasets as well as a cohort of patient samples." (PMID 38540693, 2024). "We also found significant association of the low claudin-2 expression with poor patient survival, based on the overall survival, tumor grade or patient gender." (PMID 33622361, 2021). "Our previous work implicated the first extracellular loop of Claudin-2 as an essential determinant for tumor cell-hepatocyte interactions and liver metastasis." (PMID 34079064, 2021). "The key findings of the present study are that claudin-2 is expressed in CAFs in primary tumor tissue of mCRC in a manner which is linked to KRAS mutation status and progression-free survival." (PMID 29134439, 2018). "Our results show that loss of GCC signaling reduced JAM-A and Claudin-2 in vivo and vitro, which have been determined to be associated with tumor progression." (PMID 21305056, 2011). "Besides, researches on the association between CLDN2 and cancer has been steadily increasing, with a growing evidence elucidating its involvement in tumor growth, metastasis, and metabolism." (PMID 38425650, 2024). "The tumor reduction also correlated with a decrease in claudin-2 expression and may have been an underlying factor." (PMID 33758708, 2021). "Claudin-2 expression may be involved at early stages of transformation in inflammatory bowel disease-associated neoplasia." (PMID 28212604, 2017). "Moreover, forced claudin-2 expression in claudin-2 deficient CRC cells promoted in-vivo tumor growth." (PMID 29152115, 2017). "Other claudins that were up-regulated in the tumor samples were CLDN2 and CLDN7, and these genes might also be implicated in gastric carcinogenesis." (PMID 24321518, 2013). "Descriptive co-occurrence and correlation analyses demonstrated concordant spatial relationships among CLDN-2 expression, tumor budding, nodal involvement, lymphovascular invasion, and compartment-specific E-cadherin patterns." (PMID 42279354, 2026). "As some members of the zonula occludens proteins are thought to enable intrahepatic extravasation of circulating tumor cells, we analyzed the expression of the genes Claudin-2 and -5 as well as Occludin and ZO-1 in liver tissues in this mouse model." (PMID 38919609, 2024). "For instance, overexpression of claudin-2 in human colon cells increased proliferation in vitro and accelerated tumor growth in vivo." (PMID 39776762, 2024). "Overexpression of claudin-2 in RCC-derived tumor cells repressed tumor formation/growth in mouse xenografts." (PMID 39123485, 2024). "In the tumor tissue of the TH mice, an increase in Cldn2 expression was observed, followed by a decrease in Cldn7 and Muc13 expression." (PMID 39063041, 2024). "Comparing AT2 and CLDN2+ AT2 cells in the tumor tissues, we found that the CLDN2+ AT2 cells were with significant later pseudotimes than the AT2 cells." (PMID 37488117, 2023). "Claudin-2 overexpression inhibits mesenchymal plasticity, tumorigenic abilities, and tumor growth in murine models." (PMID 38188015, 2023). "Claudin-2 is significantly reduced in RCC samples, and loss of the protein is associated with tumor progression and poor survival." (PMID 38188015, 2023). "The CLDN2+ AT2 cells showed significantly higher proportions in tumor tissues than normal tissues, especially in the three MPLC-LUAD patients." (PMID 37488117, 2023). "CLDN2 was over-expressed in the tumor tissues of P2 and P3, and specifically located at the cytomembrane of AT2 cells." (PMID 37488117, 2023).
tumor (continued). "Meanwhile, the expressions of CLDN2 were remarkably higher in the tumor tissues than normal ones in MPLCs." (PMID 37488117, 2023). "Results showed the CLDN2 IHC scores were significantly higher in the tumor tissues of MPLCs than in IPM and solitary LUADs." (PMID 37488117, 2023). "Firstly, CLDN2+ AT2 cells were more significantly enriched in the tumor tissues than the normal tissues, especially in three MPLC-LUAD patients." (PMID 37488117, 2023). "The idea of reducing CLDN2 expression in cells by mimicking the short peptide of CLDN2’s second extracellular loop (ECL2) to improve tumor cell sensitivity to chemotherapy drugs provides us with new inspiration." (PMID 36620607, 2022). "These analyses revealed that, exclusively, the increase in claudin-2 expression is an independent significant prognostic factor for recurrence-free survival in addition to the tumor stage and lymph node status." (PMID 36232536, 2022). "The results displayed that the level of SCNN1B and RBPMS2 was significantly reduced while the expression of NFE2L3 and CLDN2 was increased in GC tumor tissues compared to paracarcinoma tissues." (PMID 35137653, 2022). "It would therefore be advisable to re-evaluate the patients with an increased expression of claudin-2 and a reduced expression of claudin-4 at shorter intervals in the follow-up assessment of the tumor." (PMID 36232536, 2022). "The average weight of mouse tumours at the time of sacrifice was heavier in mice injected with CLDN2‐overexpressing HCT116 compared to mice injected with vector control (0.76 ± 0.14 g, n = 8 vs. 0.42 ± 0.04 g, n = 8, p = .038)." (PMID 34965023, 2021). "IHC analysis of the kidney from these mice further demonstrated a sharp decrease in claudin-2 expression in the tumor with adjoining normal tissue demonstrating robust claudin-2 expression." (PMID 33622361, 2021). "Our results demonstrate a novel kidney specific tumor suppressive role for claudin-2 protein and further demonstrate that claudin-2 co-operates with the YAP signaling in regulating the RCC malignancy." (PMID 33622361, 2021). "Additional inquiry using a panel of large surgically removed RCC specimen further verified a sharp decrease in claudin-2 expression in the tumor and adjacent fibrotic areas." (PMID 33622361, 2021). "To validate further that claudin-2 serves a tumor-suppressive role in RCC, we utilized RCC-derived Caki-2 cells." (PMID 33622361, 2021). "And a subsequent research group detailed CLDN2 expression as the essential mediator in the tumour‐promoting role of symplekin." (PMID 34965023, 2021). "Following splenic injection, Claudin-2 overexpressing cells (Cldn2OE) showed a higher tumor burden in the liver when compared with their respective controls." (PMID 34079064, 2021). "Claudin-2 overexpression resulted in striking inhibition of the tumor formation and growth by Caki-2 cells (290 ± 1.2 mm3 versus 3 ± 0.6 mm3), at the time of mice sacrifice (3weeks from the time of subcutaneous injection)." (PMID 33622361, 2021). "The tumor suppressive effects of claudin-2 expression were lost upon deletion of its PDZ-binding motif emphasizing the critical role of the PDZ-domain in claudin-2 interaction with YAP in regulating RCC malignancy." (PMID 33622361, 2021). "In the present study, utilizing a combined in vitro and in vivo approach, including mouse models of renal tumorigenesis and RCC patient data, we have discovered a novel tumor suppressive role for claudin-2 in RCC." (PMID 33622361, 2021). "Interestingly, our findings that claudin-2 physically interacts with YAP, and the loss of the PDZ-domain of claudin-2 not only disrupts this association but also the tumor-suppressive effects of claudin-2, suggest claudin-2 may regulate YAP-activation through its partnering." (PMID 33622361, 2021).
tumor (continued). "Based on the results from clinical CRC tissues and public TCGA databases, our study revealed increased CLDN2 expression in CRC tumours compared with paired adjacent normal mucosa and predicted shorter overall survival in CLDN2‐high patients." (PMID 34965023, 2021). "We totally identified 54 differentially expressed tumour‐related genes from comparison between CRISPR‐mediated CLDN2 knockout cell and vector control cell." (PMID 34965023, 2021). "Further analysis of protein expression using Clinical Proteomic Tumor Analysis Consortium (CPTAC) database revealed a similar progressive decrease in claudin-2 protein expression with RCC progression." (PMID 33622361, 2021). "Intensity scoring for claudin-2 expression in RCC patient samples by a pathologist further showed significant decreases in the tumor versus normal kidney." (PMID 33622361, 2021). "Many of the genes upregulated in these tumor initiating cells were expressed in our Cluster 1 cells including Tff3, Tspan8, Gpc3, Ly6d, Cldn2." (PMID 33173221, 2020). "In the tumor stroma, we observed heterogeneous pattern of claudin-2 expression in macrophages with the presence of CD68+/cl2−, CD68+/cl2+ (see Fig. 1D2), CD163+/cl2− and CD163+/cl2+ cells (see Supp Fig.3B1 and C)." (PMID 29134439, 2018). "Apart from the claudin-2-positive macrophages and vessels, additional dispersed dot-like claudin-2 expression was detected in other cells of the tumor stroma." (PMID 29134439, 2018). "Future studies should also consider the possibility that the oxaliplatin-treated cases represent a subgroup of CRC where claudin-2 expression is related to intrinsic tumor aggressiveness." (PMID 29134439, 2018). "In turn, the over expression of claudin-2 along with EphA2 promotes A549 cell proliferation and tumor growth." (PMID 22824143, 2012). "Our study suggests that EphA2 signaling up-regulates the expression of the TJ-protein claudin-2 that plays an important role in promoting cell proliferation and tumor growth in NSCLC cells." (PMID 22824143, 2012). "The novel finding of our present study is that receptor EphA2 mediated the enhanced induction of functionally altered claudin-2 via down-regulation of tumor suppressor gene expression cdx-2 in NSCLC cells." (PMID 22824143, 2012). "The over expression of cdx-2 by vector pcMV-cdx-2 resulted in downregulation of claudin-2 and attenuation of cell proliferation and tumor growth on matrigels." (PMID 22824143, 2012). "Ephrin-A1 activation or transfection of cells with plasmid containing the ephrin-A1 construct inhibits the expression of claudin-2 confirming its anti-tumor effects on NSCLC cells." (PMID 22824143, 2012). "It is plausible that over expression of receptor EphA2 promotes claudin-2 which in turn enhances tumor colonization of A549 cells." (PMID 22824143, 2012). "We report a novel mechanism of ephrin-A1 mediated attenuation of NSCLC tumor growth due to down regulation of claudin-2 and induction of tumor suppressor gene cdx-2." (PMID 22824143, 2012). "In this study, we attempted to understand the underlying mechanisms by which EphA2 over expression leads to enhanced or irregular claudin-2 expression via cdx-2 modulation and promote tumor growth in NSCLC cells." (PMID 22824143, 2012). "Cldn2 (claudin 2) has been shown to modify tumor invasion by the regulation of matrix metalloproteinases (MMPs)." (PMID 19812696, 2009). "CLDN-2-higher tumors exhibited increased tumor budding and spatially selective adhesion remodeling, characterized by reduced membranous E-cadherin at the invasive front and budding sites, with more preserved membranous epithelial organization within metastatic lymph-node deposits." (PMID 42279354, 2026). "PRMTs may promote tumor development by influencing immune escape through the CLIC6/CLDN2/BPIFB1 axis." (PMID 40399547, 2025).
tumor (continued). "In TH mice, CAC was characterized by a decrease in Muc13 and Cldn7 expression and an increase in Cldn2 expression in the tumor tissue of the distal colon in comparison with the control group, while the expression of Muc13 and Cldn7 in the peritumoral area was higher relative to the tumors." (PMID 39063041, 2024). "By IHC, significant intra- and inter-tumor variability in CLDN2 staining was seen." (PMID 38540693, 2024). "We also demonstrated the overexpression of different CLDNs, especially CLDN2, -3 and -4, and -7 as has already been described in other tumor types, which might serve as a therapeutic target." (PMID 37621953, 2023). "Patients with an increase in claudin-2 expression lived for an average of 12 months without recurrence, in contrast to patients with approximately the same expression of claudin-2 in healthy and in tumor tissue of the oral cavity, who were free of recurrence, on average, for 34 months." (PMID 36232536, 2022). "All these effects might contribute to tumor growth and invasion and thereby shorten relapse-free survival in patients with increased claudin-2 expression of OSCC." (PMID 36232536, 2022). "Taken together, these data validated a tumor suppressive role for claudin-2 in RCC." (PMID 33622361, 2021). "Moreover, we generated in vivo mouse xenograft model and found that knockout of NDRG1 in CLDN2‐absence context resulted in bounce back of the subcutaneous tumour size from shrank." (PMID 34965023, 2021). "Though IHC analysis of clinical primary tumour and paired liver metastasis both showed high expression of CLDN2 without statistical difference between groups, patients with increased CLDN2 levels in primary tumour developed more with liver metastasis within 5 years." (PMID 34965023, 2021). "Since p27kip1 has tumor suppressor effects, its regulation by claudin-2 might be relevant for carcinogenesis." (PMID 31726679, 2019). "In this type of tumor, claudin-2 expression appears to correlate with metastasis formation." (PMID 31726679, 2019). "When considering both markers simultaneously, patients were stratified into four groups according to Claudin-2 and Afadin expression within the primary tumor: Claudin-2low/Afadinlow, Claudin-2low/Afadinhigh, Claudin-2high/Afadinlow, and Claudin-2high/Afadinhigh." (PMID 30692208, 2019). "The precise molecular mechanisms through which Claudin-2 and Afadin contribute to these phenotypes require further experimentation and may shed light on the opposing roles of these cancers in different tumor types." (PMID 30692208, 2019). "It was also reported that claudin-2 expression may be lost during certain stages of the metastatic process, such as early dissemination from the primary tumour." (PMID 25598217, 2015). "Indeed, Claudin-2 enables integrin-dependent tumor cell adhesion to the extracellular matrix components and integrin-independent tumor cell adhesion to hepatocytes." (PMID 25823815, 2015). "Moreover, silencing the expression of receptor EphA2 by siRNA significantly reduced claudin-2 expression and decreased cell proliferation and tumor formation." (PMID 22824143, 2012). "Furthermore, silencing cdx-2 gene expression before ephrin-A1 treatment increased claudin-2 expression along with increased cell proliferation and tumor growth in A549 cells." (PMID 22824143, 2012). "In the present study we hypothesized that EphA2 signaling modulates claudin-2 gene expression via induction of cdx-2, a tumor suppressor gene in NSCLC cells." (PMID 22824143, 2012). "Notably, Cldn2, Fetub, Fst, Orm1, S100a14 and RasGRF1 were primarily detected in the cytoplasm of bronchial normal cells and tumor cells." (PMID 19812696, 2009). "Moreover, this CLDN2+ AT2 cell type preferred to aggregate spatially in the tumor tissues." (PMID 37488117, 2023). "Thus, an attractive hypothesis is that claudin-2 may increase proliferation/survival and migration of fibroblasts and macrophages in the tumor environment." (PMID 31726679, 2019).
tumor (continued). "We therefore hypothesized that reduction of claudin-2 expression could reduce the CRC tumor burden." (PMID 29152115, 2017). "CLDN2, significantly upregulated in NSCLC tissues versus paired normal tissues, promoted tumor cell proliferation and cisplatin resistance by upregulating multidrug resistance-associated protein 2 (MRP2)." (PMID 41981457, 2026). "We found that between normal and tumor samples, CLDN8 and CLDN23 were downregulated and CLDN1 and CLDN2 were upregulated, respectively." (PMID 37799140, 2023). "The expressions of ITPR2, MDM2, KRAS and CDK4 were also highest in the CLDN2+ AT2 cells, and higher in the tumor-derived CLDN2+ AT2 cells than the normal ones." (PMID 37488117, 2023). "Previous studies exploring the effects of CLDN1, CLDN2, CLDN4, CLDN11, CLDN12, CLDN14, and CLDN23 expression on CRC tumor growth have yielded findings consistent with our results in the present study." (PMID 35281827, 2022). "Analyzes of the relationship between HHE genes and the tumor site in the colon region indicated that four genes, including DUSP4, ZIC2, CD55, and CLDN2 significantly increased in the cecum region (FDR < 0.01)." (PMID 36064367, 2022). "Overexpression of claudin-2 in RCC-derived cancer cells inhibited tumorigenic abilities and xenograft tumor growth." (PMID 33622361, 2021). "In this study, we found that CLDN2 expression was significantly elevated in CRC patients and was also closely related to tumour metastasis and patient survival." (PMID 34965023, 2021). "Animal studies can also be performed where 5FU/oxaliplatin-sensitivity can be analyzed in tumor xenografts formed after coinjection of CRC cells and CAFs of defined claudin-2 status." (PMID 29134439, 2018). "CLDN1 and CLDN2 stained positive in 10–50% of tumor cells, while CLDN4 and CLDN7 stained positive in ≥50% of tumor cells." (PMID 25393310, 2014). "It is worth emphasizing that significant CLDN2 expression was observed in ACC, which is contrary to what we previously observed in SCLC, where there was no CLDN2 IHC positive tumor." (PMID 37621953, 2023). "Besides, like the CLDN2+ AT2 cells, this COL6A3+ fibroblast subtype was also more significantly enriched by the tumor tissues than the normal ones." (PMID 37488117, 2023). "For claudin-2, which is upregulated in OSCC, the tumor tissue from group 1 had nearly as much claudin-2 as the control tissue; groups 2 and 3 showed a higher expression of claudin-2 in the tumor tissue." (PMID 36232536, 2022). "It was also suggested that CLDN2 may act via EGFR transactivation and that forced claudin-2 expression leads to increased proliferation of cells and significantly greater tumor growth in vivo." (PMID 34822542, 2021). "Macrophages in peritumoral stroma, not adjacent to the tumor, were predominantly claudin-2-negative (see Supp Fig.3B2)." (PMID 29134439, 2018). "In addition, Claudin-2, a unique member of the claudin family of transmembrane proteins which is significantly increased in CRC and correlates with cancer progression and tumour growth, is regulated in Caco-2 via EGF." (PMID 24180698, 2013). "It is likely that the high Cldn2 expression in the TH animals promoted intestinal epithelial tissue regeneration, which was highly sensitive to AOM and DSS, and inflammation accompanying tumor growth led to a decrease in the number of goblet cells and, as a consequence, Muc13 expression." (PMID 39063041, 2024). "Various genes that were significantly changed, such as CD79B, CLDN2, SPP1 and IGHG3 were the marker genes of the identified cell types or sub-populations, probably owing to the high heterogeneity in cellular compositions across the tumor samples, as observed above." (PMID 37488117, 2023).